AP5M1 (adaptor related protein complex 5 subunit mu 1)
Description:
As part of AP-5, a probable fifth adaptor protein complex it may be involved in endosomal transport. According to PubMed:18395520, it may play a role in cell death.
Synonyms: Mu5; MuD; C14orf108; MUDENG; FLJ10813
Tractability: Antibody: UniProt places it where antibodies can reach, with high confidence. PROTAC: ubiquitination databases record sites on it; its protein half-life has been measured.
Gene: Protein-coding gene on chromosome 14 (57,268,504 to 57,298,742, forward strand). Ensembl gene ENSG00000053770.
Subcellular location: Cytoplasm, cytosol; Late endosome membrane; Lysosome membrane
Gene Ontology:
Biological process: endosomal transport; lysosome organization; vesicle-mediated transport
Cellular component: AP-type membrane coat adaptor complex; cytosol; late endosome; lysosome; membrane; AP-5 adaptor complex; late endosome membrane; lysosomal membrane
Genetic constraint (gnomAD): Loss-of-function variants: 24 observed, 31.82 expected, observed/expected ratio (o/e) 0.75, 90% interval 0.55 to 1.06. The upper end of that interval is the gene's LOEUF score, 1.06, which puts it in group 4 of 6, group 1 being the genes least tolerant of losing a copy. Missense variants: 404 observed, 445.79 expected, observed/expected ratio (o/e) 0.91, 90% interval 0.83 to 0.98. Synonymous variants: 160 observed, 159.06 expected, observed/expected ratio (o/e) 1.01, 90% interval 0.88 to 1.15.
Homologues: Orthologues: chimpanzee AP5M1 (99% identical), macaque AP5M1 (98% identical), dog AP5M1 (92% identical), guinea pig AP5M1 (90% identical), pig AP5M1 (90% identical), rabbit AP5M1 (87% identical), mouse Ap5m1 (85% identical), rat Ap5m1 (85% identical), tropical clawed frog ap5m1 (58% identical), zebrafish ap5m1 (55% identical).
Diseases named in the same sentence as AP5M1 in open-access papers:
AP5M1 is named in the same sentence as 20 diseases in open-access papers, as found by Europe PMC text mining. Sharing a sentence is not in itself a finding about the gene and the disease. The quoted sentences say what the papers report.
cervical carcinoma (2 papers, 2020 to 2021). A carcinoma arising from either the exocervical squamous epithelium or the endocervical glandular epithelium. "AP5M1 induces apoptosis in cervical carcinoma cells and may play a similar role in primordial follicle death and premature loss of ovarian reserve." (PMID 34199109, 2021). "They demonstrated the potency of AP5M1 to induce apoptosis in cervical cancer cells." (PMID 32759789, 2020).
gastric tumor (1 paper, 2018). "Consistent with our results, we also found overexpression of lncRNAs such as H19, GAS5, TUG1, AP5M1 and MALAT1 and downregulation of LINCROR, POU3F3, HOTAIR, FALEC, NBAT1, and ZEB2-AS1 lncRNAs in TCGA gastric tumor datasets." (PMID 29719612, 2018). "Consistent with our data, the lncRNAs H19, GAS5, TUG1, AP5M1, and MALAT1 were found to be overexpressed in TCGA database gastric tumors." (PMID 29719612, 2018).
lymphoma (1 paper, 2020). A malignant (clonal) proliferation of B- lymphocytes or T- lymphocytes which involves the lymph nodes, bone marrow and/or extranodal sites. "MuD, also known as the adaptor-related protein complex 5 subunit mu 1 (AP5M1), was originally identified to induce cell death in lymphoma cell lines." (PMID 32759789, 2020).
retinal disease (1 paper, 2025). "In summary, through a large multi-national collaborative effort involving multiple centers, we have identified pathogenic variants in the genes AP5Z1, AP5M1, and AP5B1 as an independent cause of a recessive form of retinal disease characterized by the progressive loss of macular photoreceptors." (PMID 40081374, 2025).
hereditary disease (1 paper, 2025). A disease that is caused by genetic modifications where those modifications are inherited from a parent's genome. "Conversely, AP5M1 and AP5B1 were not previously associated with any human hereditary disease." (PMID 40081374, 2025).
AP5M1 also shares sentences with these, for which no sentence is quoted: cancer (7 papers); astroglioma (2); glioblastoma (2); glioma (2); tumor (2); brain tumor (1); breast invasive carcinoma (1); ependymoma (1); esophageal carcinoma (1); gastric cancer (1); HIV-1 infection (1); kidney cancer (1); oligodendroglioma (1); renal carcinoma (1); skin cancer (1).